SCARB2 (scavenger receptor class B member 2)
Diseases named in the same sentence as SCARB2 in open-access papers (continued):
Sharing a sentence is not in itself a finding about the gene and the disease.
infection (continued). "In this study, through LDH release and MTT assays, we demonstrated that a MOI of 1.5 oncolytic virus EV-A71 has moderate cytotoxicity on GBM cells and EV-A71 infection inhibited GBM cell proliferation via regulating SCARB2 expression." (PMID 41210942, 2025). "Nonetheless, we found that SCARB2-KO prevents virus replication both in RD cells and in Jurkat cells, consistent with a variety of evidence supporting an essential role in infection for SCARB2." (PMID 38359079, 2024). "(D) For sSCARB2 inhibition assay, viruses (MOI 0.5) were incubated 1 hr at 37 °C with 1 μg of soluble scavenger receptor class B member 2 (SCARB2) (sSCARB2) before infection of Vero cells." (PMID 39714930, 2024). "The results suggest that non-SCARB2 receptors are responsible for virus attachment and internalization, whereas SCARB2 within late endosomes and lysosomes is an intracellular receptor essential for a subsequent event in infection." (PMID 38359079, 2024). "Nonetheless, SCARB2 was readily detected on late endosomes and lysosomes, and is essential for productive infection." (PMID 38359079, 2024). "Expression of human SCARB2 in murine cells or in transgenic mice permits infection by EV-A71, clearly demonstrating its importance to infection." (PMID 38359079, 2024). "Taken together, the results indicate that, at least in Jurkat cells, SCARB2 functions primarily at a post-attachment step in infection." (PMID 38359079, 2024). "Although a variety of receptor molecules have been proposed to mediate EV-A71 infection, one of them, SCARB2, is widely believed to serve as the primary attachment and entry receptor on many cell types." (PMID 38359079, 2024). "To examine the role of PSGL-1 and SCARB2 in EV-A71 infection more strictly, we used the CRISPR/Cas9 system to knock out the expression of either PSGL-1 or SCARB2 in Jurkat cells." (PMID 38359079, 2024). "CVA10 does not use the common enterovirus 71 (EV71) receptor, human SCARB2 (hSCARB2, scavenger receptor class B, member 2), for infection but instead uses another receptor, such as KREMEN1." (PMID 37112912, 2023). "The results showed that knockdown of Scarb2, Pik3c3, and Sirt2 resulted in a significant decrease of the parasite load in comparison to control cells after 48 h of infection." (PMID 37915600, 2023). "Among them, HS and SCARB2 protein were found to play important roles in the initial infection stage." (PMID 34583708, 2021). "EV-A71 naturally infects and replicates in human cells, but the infection efficiency in mouse cells is extremely low because EV-A71 cannot use mouse SCARB2 as a receptor." (PMID 34452525, 2021). "Using the labeled viruses, the functions of two EV71 receptors during infection, SCARB2, and heparan sulfate (HS) were comparatively studied." (PMID 34583708, 2021). "Our study provides a dynamic infection process and direct evidence of the distinct functions of HS and SCARB2 in EV71 infection." (PMID 34583708, 2021). "The results suggest that hWARS-mediated infection is a new pathway distinct from SCARB2-mediated infection." (PMID 31924205, 2020). "This region of the SCARB2 protein corresponds to the head region and determines species-specific infection of cultured cells by EV-A71." (PMID 31924205, 2020). "The anti-vimentin antibody and an anti-SCARB2 antibody had an additive effect on inhibition of EV-A71 infection." (PMID 31924205, 2020). "The region of SCARB2 required for EV-A71 binding and infection was identified using chimeric mutants of human and mouse SCARB2." (PMID 31924205, 2020). "Natural mutant EVA71 VP1 BC loop (97R167G) variants acquire nerve cell tropism, which leads to an increased ability to bind HSPG and a relatively high expression level of HSPG in neurons and glial cells, although the infection still depends on SCARB2." (PMID 33298183, 2020).
infection (continued). "The authors conclude that HS binding and in vivo virulence are negatively correlated due to trapping and abortive infection of HS-dependent viruses in tissues expressing high levels of HS but low levels of SCARB2." (PMID 30075025, 2018). "Experiments using a series of chimeric proteins between human and mouse SCARB2 identified that amino acids 142–204 of human SCARB2 (encoded by human SCARB2 exon 4) are responsible for EV71 binding and infection." (PMID 30395634, 2018). "Infection of EV-A71 in mouse models proved ineffective, owing to an incompatible murine scavenger receptor class B2 (SCARB2) receptor protein used for virus binding in humans." (PMID 29386095, 2018). "For instance, 172Q and adjacent amino acids in the EF loop are required for binding to human SCARB2 and for efficient infection of cells expressing this receptor while K98E, E145A and L169F substitutions confer binding ability to murine SCARB2." (PMID 30075025, 2018). "Members of the HEV-A sub-genus can be divided into two major groups based on their requirement of SCARB2 for infection, with EV71, CVA7, CVA14 and CVA16 using SCARB2." (PMID 24986489, 2014). "Therefore, in this study, SCARB2 gene was introduced into 293, RD and Vero cells separately via a lentiviral expression vector and the susceptibility of stable SCARB2-overexpressing cells to infection by EV71 and CA16 would be significantly enhanced compared with the parental cells." (PMID 23919614, 2013). "The interaction between STEAP3 and SCARB2 increased at 0 and 1 h post-EV-A71 infection." (PMID 40836050, 2025). "Among these proteins, PSGL-1 and SCARB2 are essential for EV-A71 absorption and infection." (PMID 39767680, 2024). "Therefore, we would expect that if SCARB2 is expressed on the surface of Jurkat cells, and interaction with SCARB2 leads to infection, EV-A71 with VP1-145E should efficiently infect Jurkat cells, even though it does not bind to PSGL-1." (PMID 38359079, 2024). "We were unable to detect SCARB2 on the surface of susceptible cells and we found that anti-SCARB2 Ab had no inhibitory effect on virus binding or infection." (PMID 38359079, 2024). "We also examined whether the anti-SCARB2 pAb inhibited EV-A71-EGFP infection in a dose-dependent manner, as reported in the previous study." (PMID 38359079, 2024). "To further test the roles of PSGL-1 and SCARB2 in EV-A71 infection of Jurkat cells, we examined the replication of EV-A71-EGFP, a PSGL-1–binding isolate (SK-EV006) engineered to express enhanced green fluorescent protein (EGFP) in infected cells, which had been used in the previous study." (PMID 38359079, 2024). "Our data highlighted that both MP4 and MP4-97R/167G enter via a SCARB2-dependent pathway, and localize in early endosomes at early times post-infection but exhibit distinct sensitivities to HCQ, a feature independent of their differential use of HS as an attachment receptor." (PMID 39714930, 2024). "Interestingly, at 48 h post-infection, a significant decrease of parasite load of 44%, 32%, and 26% was observed after knockdown of Scarb2, Pik3c3, and Sirt2, respectively." (PMID 37915600, 2023). "Accordingly, we performed a series of methods to determine whether the antiviral activity of Aβ1–42 was related to SCARB2, which was an attachment and uncoating glycoproteins for EV-A71 infection." (PMID 36127711, 2022). "SCARB2 is pivotal in EV-A71’s attachment and uncoating, facilitating efficient EV-A71 infection." (PMID 36127711, 2022). "EV-A71 cannot use mouse SCARB2 as a receptor, and adult mice are not susceptible to infection by EV-A71." (PMID 34452525, 2021). "This study speculated that the expression level of SCARB2 might be related to virus sensitivity and infection rate." (PMID 34193186, 2021). "Thus, two mouse models that express SCARB2 via a ubiquitous promotor are less vulnerable to EV-A71 infection." (PMID 31924205, 2020).
infection (continued). "Adult mice are not susceptible to infection by EV-A71, but transgenic mice that express human SCARB2 become susceptible to EV-A71 infection and develop neurological diseases similar to those observed in humans." (PMID 31924205, 2020). "In vivo, SCARB2 expression was observed in EV-A71 antigen-positive neurons and epithelial cells in the crypts of the palatine tonsils in patients that died of EV-A71 infection." (PMID 31924205, 2020). "In our lethal infection study, SCARB2-Tg mice immunized with two doses of EV-A71 formulated with PS-G as an adjuvant could protect against a lethal EV-A71 intragastrical challenge." (PMID 33117346, 2020). "To determine whether MADAL385 affects attachment to PSGL1 and HS during infection, we employed human SCARB2- or PSGL1-overexpressing L929 cells." (PMID 31071193, 2019). "In addition to viral binding and internalization, SCARB2 is capable of viral uncoating, whereas PSGL-1 is not, which explains why mouse L cells expressing PSGL-1 have a lower infection EV71 efficiency of than those expressing SCARB2." (PMID 30395634, 2018). "As miR‐127‐5p‐mediated downregulation of SCARB2 likely impact only on the uninfected cells for their susceptibility to EV71 infection, it is likely that reduced infection is mainly resulted from decreased viral attachment to the cells with miR‐127‐5p‐mediated SCARB2 downregulation." (PMID 28593131, 2017). "However, infection rate here was normalized against the control siRNA pools for SCARB2 and NT in each plate before HRFs or HSFs were determined." (PMID 27748395, 2016). "Results from the infection inhibition assay showed that pre-treatment of RD cells with the anti-SCARB2 antibody blocked EV71 infection in a dose-dependent manner as the virus titre was significantly reduced by ~1.5 log at the highest concentration of anti-SCARB2 antibody used." (PMID 25747578, 2015). "Surprisingly, in contrast to the results of previous studies, we found that SCARB2 is absent from the surface of RD cells and other susceptible cell lines we examined, and that although SCARB2 is essential for infection of these cells, it is dispensable for virus attachment." (PMID 38359079, 2024). "Finally, we examined the role of SCARB2 in EV-A71 infection of human primary cells." (PMID 38359079, 2024). "Therefore, under certain conditions, receptors other than SCARB2, called attachment receptors, may assist the virus, and enable efficient infection." (PMID 34452525, 2021). "Therefore, SCARB2 is thought to play an essential role in infection in vivo." (PMID 31924205, 2020). "Other mammals, especially small rodents, are not susceptible to infection primarily due to the incompatibility of the virus with the receptor protein expressed on rodent cells—which had been identified recently as SCARB2 (Scavenger Receptor Class B, Member 2) protein." (PMID 27357918, 2016). "As revealed by the MTT assays, EV-A71 infection led to inhibited cell growth of GBM cell line, while SCARB2 knockdown further inhibited the malignant features (H p < 0.05, p < 0.01, p < 0.001)." (PMID 41210942, 2025). "Then, to confirm the role SCARB2 and ANXA2 play in EV-A71 infection, a blocking experiment was carried out in tree shrew brain MVECs." (PMID 40642060, 2025). "EV-A71 utilizes various receptors, including P-selectin glycoprotein ligand-1 (PSGL-1), scavenger receptor class B member 2 (SCARB2), annexin II, sialic acid, nucleolin, and heparan sulfate, to facilitate infection." (PMID 39767680, 2024). "One such antibody is JL2, which can compete with EV-A71 to bind to the extracellular region of human SCARB2(PDB: 5XBM), thereby effectively inhibiting EV-A71 infection in target cells." (PMID 37001813, 2024). "Identification of SCARB2 and PSGL-1 as receptors for EV-A71 infection paves the avenue toward understanding the interaction between EV-A71 and host cells." (PMID 30563052, 2018). "SCARB2 can acts as a receptor for all strains of EV71 and is considered the critical receptor for infection." (PMID 29238324, 2017).
infection (continued). "Examination of viral growth kinetics by measuring CCID50 revealed that virus attachment in the first step of infection (primary infection) and replication of EV71 and CA16 were more efficient when cells overexpressed the SCARB2 protein." (PMID 23919614, 2013). "We expressed human SCARB2 gene in NIH3T3 cells (3T3-SCARB2) to study the mechanisms of EV71 entry and infection." (PMID 22272359, 2012). "Recent study has mapped the encoding sequence at the region of amino acid 142 to 204 of human SCARB2 that is critical for EV71 binding and infection." (PMID 22272359, 2012). "Further, we found that although SCARB2 is necessary for infection of Jurkat cells, it is neither expressed on the cell surface nor involved in EV-A71 attachment." (PMID 38359079, 2024). "Amino acid residues 142–204 of SCARB2 are critical for EV71 attachment and cellular infection." (PMID 39335111, 2024). "Taken together, the results with RD-SCARB2-KO cells confirm that SCARB2 is not required for virus attachment to RD cells, but is instead essential for a post-attachment step in infection." (PMID 38359079, 2024). "The authors of these studies concluded that binding to HS on endothelial cells in the absence of SCARB2 leads to viral trapping, abortive infection, and attenuation." (PMID 39714930, 2024). "We hypothesized that in Jurkat cells, infection requires attachment to PSGL-1 at the cell surface, but that uncoating depends on a subsequent intracellular interaction with SCARB2." (PMID 38359079, 2024). "TMEM106A blocks SCARB2-mediated EV-A71 and CV-A16 infection but does not affect infections mediated by other receptors." (PMID 35359978, 2022). "In the absence of SCARB2, human tryptophanyl-tRNA synthetase (WARS) can make cells susceptible to infection by EV-A71." (PMID 33499355, 2021). "On the other hand, HS plays a more important role in cell binding but cannot enable successful infection and replication without SCARB2." (PMID 34583708, 2021). "Although heparan sulfate proteoglycans are expressed by many cultured cell lines and enhance infection by a subset of EV-A71 strains, they are not expressed by cells that express SCARB2 at high levels in vivo." (PMID 31924205, 2020). "This was also shown by transfection of human SCARB2 in mouse L929 cells that are non-permissive for infection by EV71." (PMID 30075025, 2018). "A striking reduction in viral titers was observed in SCARB2 knockout RD and Caco-2 cells for EV71-VP197L167E and EV71-VP197R167G suggesting that both variants depend on this receptor for effective infection regardless of the cell line." (PMID 30075025, 2018). "We compared the sequences of mouse and human SCARB2 and highlighted the apical domains on the top of the SCARB2 molecules, that potentially bind to EV71 and facilitate its entry and infection." (PMID 28447294, 2017). "As expected, EV-A71 infection of these primary cells was not inhibited by anti-SCARB2 pAb." (PMID 38359079, 2024). "Additionally, SCARB2 plays an important role in Coxsackievirus A10 (CVA10) infection, as siRNA-mediated suppression of SCARB2 expression in RD cells was shown to lead to a marked decrease in CVA10 VP1 expression after infection." (PMID 39335111, 2024). "Specific siRNA targeting hSCARB2 could not completely inhibit CVA10 infection in RD cells, even though the expression level of SCARB2 was impaired." (PMID 37112912, 2023). "Interestingly, even in the presence of SCARB2, knockdown of WARS in a human rhabdomyosarcoma cell line (RD) or knockout of WARS in a human neuronal cell line (NT2) still inhibited effective EV-A71 infection." (PMID 33499355, 2021). "The viral uncoating receptor SCARB2 and various attachment factors (such as PSGL1, annexin II, DC-SIGN, nucleolin, vimentin, heparin sulphate and sialic acid) have been described to play a role in EV-A71 infection, either by increasing virus attachment or by mediating the uncoating process." (PMID 31339457, 2019).
infection (continued). "It is equally interesting to note that multiple CV-A16 virus strains could cause a lethal infection in the neonatal mice, despite the fact that mouse PSGL-1 and SCARB2 are not expected to mediate efficient replication of CV-A16 viruses in these mice." (PMID 24736564, 2014). "Thus anti-PSGL-1 but not anti-SCARB2 Ab inhibited both virus binding and infection in Jurkat cells." (PMID 38359079, 2024). "Therefore, despite the fact that the SCARB2 expression levels in brain and muscles of transgenic mice are contrary to that in humans, CA16 infection exhibited neurotropism rather than muscle tropism in the hSCARB2 mice model." (PMID 33882964, 2021). "Human SCARB2 amino acid residues 142–204 are important for EV71 binding and infection." (PMID 28447294, 2017). "Since L929 cells do not express SCARB2 and PSGL-1, our observations suggest that exosomal viral RNA could overcome the restriction of the entry receptor and mediate productive infection of the host cells in a receptor independent manner." (PMID 28910400, 2017). "As mouse PSGL-1 and SCARB2 are not expected to mediate efficient replication of CA16 viruses in these mice, our study raises the question of whether additional cellular receptors contribute to CA16 infection in our mouse model." (PMID 24496826, 2014). "In particular, the binding interfaces of SCARB2 and EV71 have not been determined, although SCARB2 is suggested to bind to the “canyon” of EV71 particles like other uncoating receptors, and importance of acidic pH conditions in establishment of infection was unclear." (PMID 25099349, 2014).